PAN3 (poly(A) specific ribonuclease subunit PAN3)
Description:
Regulatory subunit of the poly(A)-nuclease (PAN) deadenylation complex, one of two cytoplasmic mRNA deadenylases involved in general and miRNA-mediated mRNA turnover. PAN specifically shortens poly(A) tails of RNA and the activity is stimulated by poly(A)-binding protein (PABP). PAN deadenylation is followed by rapid degradation of the shortened mRNA tails by the CCR4-NOT complex. Deadenylated mRNAs are then degraded by two alternative mechanisms, namely exosome-mediated 3'-5' exonucleolytic degradation, or deadenylation-dependent mRNA decapping and subsequent 5'-3' exonucleolytic degradation by XRN1. PAN3 acts as a regulator for PAN activity, recruiting the catalytic subunit PAN2 to mRNA via its interaction with RNA and PABP, and to miRNA targets via its interaction with GW182 family proteins. [Isoform 1]: Decreases PAN2-mediated deadenylation, possibly by preventing progression into the second CCR4-NOT mediated stage of biphasic deadenylation. Has a significant effect on mRNA stability, generally stabilizing a subset of the transcriptome. Stabilizes mRNAs degraded by the AU-rich element (ARE)-mediated mRNA decay pathway but promotes degradation of mRNAs by the microRNA-mediated pathway. Its activity influences mRNP remodeling, specifically reducing formation of a subset of P-bodies containing GW220, an isoform of TNRC6A. [Isoform 3]: Enhances PAN2 deadenylase activity and has an extensive effect on mRNA stability, generally enhancing mRNA decay across the transcriptome by multiple pathways, including the AU-rich element (ARE)-mediated pathway, microRNA-mediated pathway and the nonsense-mediated pathway (NMD). Its activity is required for efficient P-body formation. May be involved in regulating mRNAs of genes involved in cell cycle progression and cell proliferation.
Tractability: PROTAC: ubiquitination databases record sites on it; its protein half-life has been measured.
Gene: Protein-coding gene on chromosome 13 (28,138,207 to 28,295,335, forward strand). Ensembl gene ENSG00000152520.
Subcellular location: Cytoplasm, P-body; Cytoplasm (Isoform 1); Nucleus; Cytoplasm (Isoform 3)
Pathways (Reactome):
Metabolism of RNA: Deadenylation of mRNA
Gene Ontology:
Molecular function: poly(A)-specific ribonuclease activity; protein binding; poly(A) binding; ATP binding; metal ion binding; protein kinase activity; RNA binding
Biological process: nuclear-transcribed mRNA poly(A) tail shortening; nuclear-transcribed mRNA catabolic process, deadenylation-dependent decay; positive regulation of cytoplasmic mRNA processing body assembly
Cellular component: cytoplasm; nucleus; PAN complex; cytosol; P-body
Genetic constraint (gnomAD): Loss-of-function variants: 13 observed, 78.74 expected, observed/expected ratio (o/e) 0.17, 90% interval 0.11 to 0.26. The upper end of that interval is the gene's LOEUF score, 0.26, which puts it in group 1 of 6, group 1 being the genes least tolerant of losing a copy. Missense variants: 804 observed, 981.63 expected, observed/expected ratio (o/e) 0.82, 90% interval 0.77 to 0.87. Synonymous variants: 386 observed, 355.45 expected, observed/expected ratio (o/e) 1.09, 90% interval 1 to 1.18.
Homologues: Orthologues: chimpanzee PAN3 (99% identical), macaque PAN3 (99% identical), dog PAN3 (97% identical), pig PAN3 (95% identical), rat Pan3 (95% identical), mouse Pan3 (94% identical), guinea pig PAN3 (83% identical), rabbit PAN3 (81% identical), tropical clawed frog pan3 (76% identical), zebrafish pan3 (66% identical), Drosophila melanogaster PAN3 (34% identical), Caenorhabditis elegans panl-3 (26% identical).
Diseases named in the same sentence as PAN3 in open-access papers:
PAN3 is named in the same sentence as 18 diseases in open-access papers, as found by Europe PMC text mining. Sharing a sentence is not in itself a finding about the gene and the disease. The quoted sentences say what the papers report.
acute myeloid leukemia (4 papers, 2018 to 2025). Acute myeloid leukemia (AML) is a group of neoplasms arising from precursor cells committed to the myeloid cell-line differentiation. "Another newly identified circRNA, circ-PAN3, has been implicated in drug resistance in acute myeloid leukemia and the self-renewal of intestinal stem cells." (PMID 39866238, 2025). "In acute myeloid leukemia, circ-PAN3 promotes drug resistance by inducing autophagy through modulating AMPK/mTOR pathway." (PMID 39866238, 2025). "CircPAN3, a circRNA generated from the PAN3 locus, has been found to maintain the self-renewal of intestinal stem cells, to modulate drug resistance in acute myeloid leukemia (AML), and to recede myocardial ischaemia/reperfusion injury." (PMID 34250050, 2021). "Notably, circ-PAN3 has been shown to positively regulate XIAP, leading to chemoresistance in acute myeloid leukemia." (PMID 39866238, 2025). "Interestingly, it has been found that circ-PAN3 can positively regulate XIAP expression, leading to chemoresistance in acute myeloid leukemia." (PMID 39866238, 2025).
leukemia (2 papers, 2017 to 2025). A malignant (clonal) hematologic disorder, involving hematopoietic stem cells and characterized by the presence of primitive or atypical myeloid or lymphoid cells in the bone marrow and the blood. "Additionally, circ-PAN3 acts as a critical mediator of chemoresistance in leukemia cells through targeting miR-153-5p and miR-183-5p-XIAP regulatory axis." (PMID 39866238, 2025). "A corresponding translocation was observed in only 31% of the leukemia cells, demonstrating that the PAN3-NONE transcript belongs to a subclone, which could explain the lower expression level observed." (PMID 29623188, 2017).
Rotavirus infection (2 papers, 2016 to 2019). Infection with any of the rotaviruses. "Furthermore, it has been shown that rotavirus infection induces the relocalization of Xrn1, Dcp1a, and PABP to the nucleus, and to sequester most of the PB components into RFs, with the exception of DDX6, Edc4, and Pan3, and to accelerate Pan3 decay by the NSP1 protein." (PMID 31681621, 2019). "A recent report showed that rotavirus infection triggers a significant time-dependent decline of PBs components XRN1, DCP1, Pan3, but not GW182." (PMID 27367717, 2016). "Pan3, but not XRN1 and DCP1, undergoes accelerated turn over in response to rotavirus infection, while XRN1 and DCP1 were translocated to the nucleus, as well as PABP." (PMID 27367717, 2016).
allergic asthma (1 paper, 2025). A asthma with a basis in a pathological type I hypersensitivity reaction. "We find that genes with many connections in this network representation, such as ADAR, PAN3, and MAPK1 have been implicated in allergic asthma before (50, –52)." (PMID 40504147, 2025).
Delusion (1 paper, 2020). A delusion is a fixed false belief held despite evidence to the contrary. "Results revealed 32 genes for adolescent PENS, of which PAN3 mapped to adolescent cognitive disorganization and schizotypy in adulthood (perceptual aberrations), and NADK2 to adolescent negative symptoms and delusions of reference in UK Biobank; none overlapped with psychiatric disorders." (PMID 32152294, 2020).
glioblastoma (1 paper, 2021). The most malignant astrocytic tumor (WHO grade IV).
hepatocellular carcinoma (1 paper, 2025). A malignant tumor that arises from hepatocytes. "However, the involvement of circ-PAN3 in hepatocellular carcinoma (HCC) is not well understood." (PMID 39866238, 2025).
poliovirus infection (1 paper, 2017). An disease or disorder caused by infection with Enterovirus C. "Poliovirus infection promotes the degradation of poly(A) specific ribonuclease subunit 3 (PAN3), a protein that initiates the deadenylation of many cellular mRNAs." (PMID 28763028, 2017).
tumor (4 papers, 2017 to 2025). "Consistent with the microarray data, circ-PAN3 expression was significantly higher in tumor samples compared to that of the normal tissues (p < 0.001)." (PMID 39866238, 2025). "It was found that circ-PAN3 expression levels were significantly correlated with tumor size, TNM staging, and lymph node metastasis." (PMID 39866238, 2025). "To validate the upregulation of circ-PAN3 in HCC, we quantified circ-PAN3 transcripts in 80 pairs of HCC tumor samples and matched adjacent normal tissues." (PMID 39866238, 2025). "In vivo silencing of circ-PAN3 significantly curtailed the tumor formation of Huh7 cells." (PMID 39866238, 2025). "Our study suggests circ-PAN3 as a tumor-promoting factor in HCC progression." (PMID 39866238, 2025). "The protein encoded by the PAN3 gene is conserved and belonged to the RAS protein family, which may indirectly inhibit excessive apoptosis by suppressing apoptosis protein activity, and inhibit tumor invasion and migration." (PMID 38433959, 2024). "To further validate the effect of circ-PAN3 knockdown on HCC tumor formation, we established an HCC tumor xenograft model in nude mice by injecting Huh7 cells, followed by the administration of si-NC and si-circ-PAN3." (PMID 39866238, 2025). "Though no common somatic variants were found between primary tumors of SBL and HB, in-frame deletion of PAN3 and ZMIZ2 were identified in both tumor samples after treatment." (PMID 35860547, 2022).
infection (2 papers, 2015 to 2026). The state of being infected such as from the introduction of a foreign agent such as serum, vaccine, antigenic substance or organism. "However, 2Apro-mediated disruption of PB was surprising, as we have previously determined it does not cleave the three PB constituents we found that undergo degradation during infection (Xrn1, Dcp1a, or Pan3)." (PMID 26610553, 2015).
cancer (1 paper, 2022). A tumor composed of atypical neoplastic, often pleomorphic cells that invade other tissues. "Among these 13 PD-L1 enhancers, except for the two cancer drivers (PAN3 and SMAD4), 11 of the enhancers belong to druggable genes." (PMID 36357569, 2022).
cardiovascular disease (1 paper, 2023). "Circular Pan3 (circPan3) derived from the poly(A) specific ribonuclease subunit PAN3 (Pan3) gene has been proved to positively contribute to cardiovascular disease." (PMID 37020518, 2023).
PAN3 also shares sentences with these, for which no sentence is quoted: ankylosing spondylitis (1 paper); melanoma (1); myelodysplastic syndrome (1); psychiatric disorder (1); schizophrenia (1); ulcerative colitis (1).